MIR5688 (microRNA 5688)
Synonyms: hsa-mir-5688
Gene: MicroRNA gene on chromosome 3 (85,385,710 to 85,385,792, forward strand). Ensembl gene ENSG00000264084.
Diseases named in the same sentence as MIR5688 in open-access papers:
MIR5688 is named in the same sentence as 1 disease in open-access papers, as found by Europe PMC text mining. Sharing a sentence is not in itself a finding about the gene and the disease.
MIR5688 shares sentences with these, for which no sentence is quoted: psychiatric disorder (1 paper).